KIR3DX1 (killer cell immunoglobulin like receptor, three Ig domains X1 (pseudogene))
Synonyms: FLJ00060; formerly LENG12
Gene: Transcribed unprocessed pseudogene on chromosome 19 (54,532,798 to 54,543,728, forward strand). Ensembl gene ENSG00000104970.
Subcellular location: Secreted
Diseases named in the same sentence as KIR3DX1 in open-access papers:
KIR3DX1 is named in the same sentence as 2 diseases in open-access papers, as found by Europe PMC text mining. Sharing a sentence is not in itself a finding about the gene and the disease.
KIR3DX1 shares sentences with these, for which no sentence is quoted: cancer (1 paper); ovarian endometriosis (1).